FOXA1 (forkhead box A1)
Diseases named in the same sentence as FOXA1 in open-access papers (continued):
Sharing a sentence is not in itself a finding about the gene and the disease.
cancer (continued). "Together this indicated that co-occupancy of FOXA1 and NKX2–1 within “normal” AEC enhancers occurred approximately three times more often than within A549 cancer-specific enhancers." (PMID 34922464, 2021). "Our data establish the importance of FOXA1 in NEPC and provide a principled approach to identifying cancer dependencies through epigenomic profiling." (PMID 33785741, 2021). "For example, FOXA1 and FOXA2, both of which play an important role in α-cell glucagon biosynthesis and secretion, are O-GlcNAc modified by OGT in cancer cells, and this modification is important for the stability of the protein." (PMID 33460647, 2021). "Truncated FOXA1 protein shows higher DNA binding affinity than the wild type FOXA1, leading to activation of WNT signaling and progression of cancer." (PMID 33810413, 2021). "Some of these TFs have been shown to exhibit oncogenic properties in various types of cancers, such as ESR1, FOXA1 and E2F1 60–62." (PMID 33850167, 2021). "FOXA1, together with EP300 and RUNX1, promotes the expression of E-cadherin, which, in turn, reduces the ability of cancer cells to trigger an EMT and initiate metastasis." (PMID 33417085, 2021). "Given that FOXM1 is an established oncogenic transcription factor which is upregulated in a variety of human cancers, we focused on characterizing the mechanism, whereby MGAT4EP/FOXA1 axis regulates its expression." (PMID 34425866, 2021). "DSCAM-AS1 can promote cancer progression by interacting with YBX1 and regulating expression of FOXA1 and ERα." (PMID 32929382, 2020). "In luminal A cancer, the hypomethylation enhances the commitment of luminal lineage at key lineage-specific markers (GATA3, ESR1, FOXA1)." (PMID 31529022, 2020). "FoxA1 and FoxA2 were mainly localized in the nuclei of normal bile duct (NBD) cells and some of the cancer cells." (PMID 32151057, 2020). "APC, FOXA1 and RASSF1A individually depicted sensitivity over 20% and specificity greater than 70%, for all cancers." (PMID 30261643, 2018). "As for CRC, the significantly higher APC, FOXA1, RARβ2, RASSF1A, SCGB3A1, SEPT9 and SOX17 methylation levels in cancer patients are in line with previous publications, although divergent results have been reported for MGMT." (PMID 30261643, 2018). "Known and predicted targets of miR-125b reported in prior studies of cancers characterized by BRAF alterations include MLK3, KLF13, CXCL11, and FOXA1." (PMID 30131528, 2018). "FOXA1 and FOXA2 are essential transcription factors in cancer as they are able to bind to their response elements in tightly wrapped nucleosomes." (PMID 28681081, 2018). "For instance, FOXA1 clearly appears to be responsible for hypomethylation of FOX-containing enhancers in breast (BRCA) and bladder (BLCA) cancers, while FOXA2 appears to be responsible in endometrial (UCEC)." (PMID 25994056, 2015). "Compared to RWPE-1, cancer cells showed stronger H3K27ac signals, and MIR1204, IER2, SMAD3, and FOXA1 were SE-associated in PC-3 and DU145 but not RWPE-1." (PMID 41330917, 2025). "FOXA1 is a key marker that helps distinguish the luminal subtype from the Ba/Sq subtype of UC tumors, and SOX2 is known to be a negative upstream regulator of FOXA1 expression in different cancers." (PMID 40643470, 2025). "The upregulation of the FOXA1 transcription factor network and the downregulation of the MTA3 pathway point to significant transcriptional reprogramming, consistent with reports that the MTA3 protein is often upregulated in cancers." (PMID 40002253, 2025). "Necroptosis induction contributes to suppressing therapeutic resistance in cancer stem cells, thus we evaluated whether the identified targets WT1 and FOXA1, which have an impact on stemness by targeting AR, could also play a role in necroptosis activation." (PMID 40399259, 2025).
cancer (continued). "FOXA1 binds directly to the promoter of DSCAM‐AS1, modulating its expression in cancer cells." (PMID 39690143, 2024). "Moreover, by using the same evaluation criteria, we identify new biomarkers whose impact on drug response spans multiple cancers, including SALL4, B2M, BAP1, CCDC6, ERBB4, FOXA1, GRIN2A, and PTPRT." (PMID 39083502, 2024). "The study also highlights that FOXA1 and FOXA2 have the same or opposite roles in several mammalian stages, which provides a theoretical basis for the future treatment of metabolic diseases, neurodegenerative diseases, and cancers by targeting FOXA1 and FOXA2." (PMID 38605023, 2024). "DSCAM-AS1 could promote cancer progression by interacting with YBX1 and regulating expression of FOXA1 and ERα." (PMID 38643469, 2024). "FOXA1- and FOXA2-mediated metabolism not only occurs under physiological conditions but is also widely found in pathological conditions, such as inflammation and cancer." (PMID 38605023, 2024). "Western blot analysis showed that intracellular TGF-β1 expression was higher in GBC tissues compared to adjacent non-cancer tissues, while FOXA1 expression was higher in adjacent non-cancer tissues than in GBC tissues in 8 cases of GBC." (PMID 38886389, 2024). "Most FOXA1 and GATA3 binding sites in HCC1954 cancer cells were located in low methylated regions." (PMID 35331302, 2022). "The role of FOXA1 in cancer remains not fully defined, as both pro- and anti-tumorigenic functions have been uncovered." (PMID 36012038, 2022). "By directly interacting with AR to influence its recruitment to discrete genomic regions, FOXA1 regulates transcriptional programs of relevance in both normal prostate tissue and cancer." (PMID 32946061, 2021). "Through the study it was concluded that the highly prospected pioneer TFs in BC, including FOXA1, TLE1, PBX1, and GATA3, possess the potential therapeutic significance and further innovations in the field could yield targeted therapy in cancer treatment." (PMID 36046086, 2021). "Many TFs, such as FOXA1 and ESR1, have been shown to function in a context-specific manner, dependent on specific protein–protein interactions, resulting in pro-oncogenic properties in some cancer types, and anti-oncogenic properties in others." (PMID 33850167, 2021). "In the Cancer Dependency Map (depmap.org), the top FOXA1 co-dependencies from the CRISPR screen data (AVANA) by Pearson correlation are SPDEF followed by ESR1 (estrogen receptor alpha) and TRPS1, underscoring the critical interplay of FOXA1 and ESR134." (PMID 33980863, 2021). "FOXA1 has been shown to have positive and negative effects on cancer progression and is also an important mediator of IGF-I mediated biological responses." (PMID 32655839, 2020). "Though many existing studies indicated the strong associations between FOXA1 expression in cancer tissues and human cancers, so far none of them focused on interactions between FOXA1 and BMI on cancers." (PMID 32207560, 2020). "Such classification is achieved based on genomic and transcriptomic analyses, which point to differential expression of specific markers among tumors: the basal cytokeratins KRT5/KRT6A and KRT14, as hallmarks of basal BlCa, and the luminal markers FOXA1 and GATA3, as hallmarks of luminal cancer." (PMID 32758253, 2020). "From the seven most promising candidates, six (APC, CCND2, FOXA1, PSAT1, RASSF1A and SCGB3A1) confirmed its cancer-specificity, discriminating normal from cancerous tissues, although with variable performance, paralleling previous observations from our team and others." (PMID 30405052, 2018). "In addition, we found several pathways enriched in long-lived genomes, including FOXA1 and FOXA transcription factor networks involved in regulating aging or age-dependent diseases such as cancer." (PMID 29883365, 2018).
cancer (continued). "Moreover, a recent study has demonstrated that FOXA1 and/or FOXA2, together with other master transcription factors, are essential for the maintenance of cancer cell states through the recruitment of the mediator–cohesin complex." (PMID 30360388, 2018). "Since APC, FOXA1 and RASSF1A were biomarkers common to BrC, CRC and LC, they were further tested as gene panel for cancer detection (designated “PanCancer”), whereas RARβ2, SCGB3A1, SEPT9 and SOX17 were considered a gene panel for discrimination of primary cancer localization (“CancerType” panel)." (PMID 30261643, 2018). "TFF3 also may contribute to cancer metastasis with epithelial-to-mesenchymal transition (EMT) potentially through the regulation of genes such as androgen receptor (AR), FOXA1 and human epidermal growth factor receptor-type 2 (HER2)." (PMID 28070169, 2017). "The correlation between AR and FOXA1 mRNA expression in the METABRIC dataset was moderately positive (Pearson r = 0.424; p < 0.001) in ER-positive cancers and strongly positive (Pearson r = 0.777; p < 0.001) in ER-negative cancers." (PMID 29137314, 2017). "Regarding the association of AR/FOXA1 status with HER2 in the present study, TMA analysis and public dataset showed no statistical significance in ER-positive cancers, although decreased HER2 protein was noted by experiments overexpressing AR or FOXA1." (PMID 29137314, 2017). "Several studies suggested that FOXA1 functions as an important antagonist of the EMT in different cancer types, but its role in NPC is not well characterized." (PMID 26934447, 2016). "Additionally there was a significant trend for early neoplasias to have a much higher fraction of cells staining positive for FOXA1 and GATA3 than normal, with positive cell fractions similar to those observed in cancer." (PMID 24887547, 2014). "This suggests that transcript 13741 may have a role in the ER/FOXA1/GATA3 pathway being activated in early neoplasias and maintaining elevated levels within cancer." (PMID 24887547, 2014). "We further investigated the effects of FOXA1 and AR on migration and invasion of EC cells, and found that neutralization of AR activity did not inhibit FOXA1-enhanced cancer cell migration or invasion." (PMID 24512546, 2014). "Our findings that ER, FOXA1, and GATA3 are all expressed at levels comparable to their matched IDC suggest that the oncogenic nature of ER pathway activation is established in the earliest stages of cancer development." (PMID 24887547, 2014). "Sub-group analysis revealed that this difference in progression free survival was only apparent in non-invasive cancers and in low grade tumors (data not shown, Log rank values for FOXA1; low grade p=0.002, high grade 3 p=0.24." (PMID 25071007, 2014). "As we found that FOXA1 alterations were also modestly frequent in breast, bladder, and salivary cancers, subsets of which also express the AR, it is logical to test our classification scheme in nonprostatic cancers moving forward." (PMID 39745364, 2025). "There are no direct FOXA1 inhibitors; however, there are many indirect mechanisms of FOXA1 inhibition being explored in other cancers, but given the conflicting reports on its expression in NEPC, it is suggested that this should not be targetable in this disease." (PMID 39682746, 2024). "In the present study, FOXA1 was found to be upregulated and has been reported to inhibit STAT2, a transcription factor and its target IFN signaling pathway in BC; this may result in cancer progression due to suppressed immune response." (PMID 37900178, 2023). "Our observation that FOXA1 expression is significantly correlated to chromatin accessibility at the SRR124–134 cluster and increases the transcriptional output of the SRR124 and SRR134 enhancers provides a mechanistic link between breast and lung developmental programs and cancer progression." (PMID 37738673, 2023). "Additionally, FOXA1 mutants can also induce EMT and enhance cancer metastasis." (PMID 35707002, 2022).
cancer (continued). "Moreover, our data further suggest that this antiviral could be effective for the treatment of those cancers, which remain addicted to the IGF1‐R/AKT/FOXA1 pathway." (PMID 36056637, 2022). "Finally, we reported physical interactions between FOXA1 with TET1 and TET2 both in an in vitro setup and in vivo at physiological levels in MCF-7 cells, adding further support for FOXA1 attracting TET1 and TET2 to induce local demethylation in cancer cells." (PMID 35440061, 2022). "Moreover, to detect the functions of FOXA1 in cancer cells in vivo, Huh7 cells with FOXA1-overexpressing and no-load plasmids were hypodermically injected into NTG mice." (PMID 35968505, 2022). "Their research demonstrated that the FOXA1 expression level in cancer tissues was significantly higher among CRC cases compared to noncancer specimens, and positive expression of FOXA1 in cancer tissues was associated with poor clinicopathological characteristics as well as poor prognosis of CRC." (PMID 32207560, 2020). "Additionally, to investigate whether LINC00482 promoted MMP15 expression by recruiting FOXA1, cancer cells were transfected with oe-NC + sh-NC, oe-LINC00482 + sh-NC, and oe-LINC00482 + sh-FOXA1." (PMID 33323547, 2020). "FOXA1 or CK14 expression greater than 1% was respectively positively and negatively correlated with overall survival (OS; p = 0.011 and p = 0.042, respectively), cancer-specific survival (CSS; p = 0.050 for both), and recurrence-free survival (RFS; p = 0.018 and p = 0.040, respectively)." (PMID 31500577, 2019). "Consistent with expectations, canonical luminal genes such as ESR1, GATA3, FOXA1, TFF1 and IGF1R were higher in ER+ samples compared to triple negative samples, while proliferation and mesenchymal genes such as SPRY2, SNAI2, FOSL1, MET and BUB1 were higher in triple negative cancers." (PMID 24520381, 2014). "However, FOXA1 also enhances a small subset of NMD-determinant exons, such as FLNA exon 30, which predicts disease recurrence, and therefore may drive a more aggressive cancer phenotype." (PMID 36170835, 2022). "The fact that the degree of association between FOXA1 staining and BCR was not as strong in our study may be due the lower degree of variability in disease aggressiveness in our patient subgroup that all have recurrent and therefore more aggressive cancer." (PMID 26986977, 2016). "FOXA1 was consistently identified as a super-enhancer target gene across all cancer cell lines, whereas in normal prostate epithelial cells (RWPE-1), FOXA1 was not SE-regulated." (PMID 41330917, 2025). "In cancer-specific enhancers in A549 cells, there was far less enrichment for both NKX2–1 and FOXA1, with no obvious differences in TF position relative to the center of the peak." (PMID 34922464, 2021). "For example, the prognostic impact of SOX9, SENP1 and mTOR was limited to ERG positive cancers while FOXA1, MTCO2 and FOXP2 were only prognostic in ERG negative cancers." (PMID 31606028, 2019). "Indeed, the role of FOXA1/AR co-expression in ER+ BC has not been investigated, although it has been suggested that the relative ratio among FOXA1, ER and AR could influence growth and aggressiveness of cancer cells." (PMID 29970021, 2018). "Although there were data available for ChIP-seq of androgen receptor (AR), FOXA1 and NKX3-1, data for TCF7L2— another transcription factor with a proposed role in prostate- and other cancers — was not available." (PMID 24497837, 2014). "Interestingly, the FOXA1-mediated repression of NR3C1 i.e. the inverse correlation between the two TFs, is not restricted to PCa but can be observed in other cancers." (PMID 38015476, 2024). "Indeed, almost 60% of cancer-specific A549 enhancers lacked any binding for FOXA1 or NKX2–1, suggesting that the colocalization of FOXA1 and NKX2–1 observed in A549 cells is primarily driven by enhancers preserved in normal tissues." (PMID 34922464, 2021).
cancer (continued). "Our data may suggest that FOXA1 keeps IGFBP-2 in check in normal cells, but this negative regulation is lost in the cancer cells." (PMID 32655839, 2020). "The results of chromatin immunoprecipitation experiments showed that both EZH2 and OGT are targeted to the promoter regions of FOXA1 and FOXC1 and knockdown of EZH2 or OGT affects expression of studied genes in breast non-malignant (MCF10A) and cancer cells (MCF7, T47D and MDA-MB-231)." (PMID 29864144, 2018). "Since FOXA1 has been described not just as a transcription factor for HER3 but also for HER2, the current work focused on interrogating JAM-A/HER2 expressional links in the context of cancer patient survival, and as a starting point to address the cell biological pathways involved." (PMID 35203384, 2022).
prostate (13 papers, 2012 to 2025). "FOXA1, a pioneer factor that maintains epithelial identity and mediates AR cistrome engagement, has been previously implicated in prostate tumorigenesis and therapeutic resistance, particularly through mutations and enhancer reprogramming." (PMID 40643528, 2025). "The field has made major strides in defining the GAIN of function effects on the AR cistrome and transcriptional program associated with prostate tumorigenesis, including redistribution of AR to enhancers enriched for FOXA1 and HOXB13 motifs." (PMID 39672812, 2024). "TLE3 was shown to co-localize with FOXA1 and AR at enhancer elements, which are selectively activated during prostate tumorigenesis, underscoring the importance of these transcription factors in this context." (PMID 31855178, 2019). "Common genetic alterations, including FOXA1 mutations, gain of the androgen receptor gene (AR amplification or mutation), and structural variants such as loss of NKX3.1 (8p21) and PTEN (10q23), account for prostate carcinogenesis." (PMID 38483933, 2024). "Alternatively, FOXA1 loss may not be important for lymph node metastases, or microenviornmental cues within the lymph node may somehow result in reactivation of FOXA1 expression." (PMID 22590586, 2012). "Investigation of the transcription factors (TFs), such as the androgen receptor and its co-regulators FOXA1 and HOXB13, known to be important in prostate tumorigenesis, revealed their involvement in the differential expression of these genes." (PMID 40525903, 2025). "Previous reports have shown that gastric differentiation program was triggered in murine lung ADC following NKX2‐1 deletion, which involved the interaction of NKX2‐1 and FOXA1/FOXA2 to re‐program FOXA1/FOXA2 binding sites and preferential activation of certain target genes." (PMID 33439550, 2021).